MEG3 (maternally expressed 3)
Diseases named in the same sentence as MEG3 in open-access papers (continued):
Sharing a sentence is not in itself a finding about the gene and the disease.
tumor (continued). "MEG3 is expressed in many normal tissues, and lost in several human tumors and tumor cell lines." (PMID 35047570, 2021). "In addition, downregulation of PIWIL1/piRNA-DQ593109 (piR-DQ593109) has been shown promote blood tumour barrier (BTB) permeability through the MEG3/miR-330-5p/RUNX3 axis." (PMID 33800703, 2021). "Additionally, PTEN, Bax and Beclin1 protein levels were up‐regulated whereas Bcl‐2 and p62 protein levels were down‐regulated in xenograft tumours from nude mice when MEG3 was overexpressed (P < .05)." (PMID 33332708, 2021). "It was observed that MEG3 expression was lower in most tumor tissues than in normal tissues." (PMID 34220951, 2021). "It is worth noting that MEG3 is a well-studied tumor suppressive lncRNA." (PMID 35201451, 2021). "Moreover, maternally expressed gene 3 (MEG3) is an acknowledged tumor suppressor that has widely been investigated in cancers including OSCC." (PMID 34885054, 2021). "MEG3 can be characterized as a tumor suppressor important in cell cycle regulation and apoptosis." (PMID 34512715, 2021). "Mechanistically, MEG3 could exert the tumor-suppressor function not only by blocking the WNT/β-catenin signaling pathway, but also by acting as a miRNA sponge of miR-548d-3p to modulate the JAK–STAT signaling pathway." (PMID 34885054, 2021). "Consistently, MEG3 overexpression inhibited the tumour formation in vivo." (PMID 33332708, 2021). "The interaction of MEG3 and tumor suppressors plays a key role in tumor invasion and metastasis." (PMID 34322395, 2021). "MEG3 inhibited miR-21-3p expression resulting in reduced tumor proliferation and invasion." (PMID 34322395, 2021). "Expression levels of POU3F3 and MEG3 were inversely correlated across tumor tissues." (PMID 35201451, 2021). "The expression of MEG3 is downregulated in numerous human primary cancers or cancer cell lines where it functions as an antitumor component or a tumor suppressor, such as glioma, liver, breast, cervical, lung, ovarian, osteosarcoma, colorectal, bladder, prostate, and gastric cancer cells." (PMID 34885213, 2021). "In this regard, lncRNAs may be considered as tumor-promoting (e.g., BANCR), when their sponging activity triggers the increase of oncogenes expression, or tumor suppressors (e.g., MEG3), when they positively regulate the expression of tumor suppressor genes." (PMID 34638331, 2021). "The relationship between MEG3 and tumor-infiltrated immune cells was analyzed using TIMER." (PMID 34220951, 2021). "Existing literature has emphasized MEG3 as a tumor-suppressing lncRNA." (PMID 34140005, 2021). "In addition, we found in the GEPIA database that MEG3 is downregulated in tumor tissues, which is the opposite of the expression trend of LINC01667." (PMID 34458133, 2021). "Prognostic value: Lower MEG3 expression was associated with higher WHO grade, older age at the time of diagnosis, low Karnofsky performance score (KPS), isocitrate dehydrogenase (IDH) wild-type, tumor recurrence, and poor overall survival." (PMID 34322395, 2021). "A maternally expressed gene (Meg3) acts as a tumor suppressor in multiple cancers including CRC." (PMID 34934045, 2021). "lnc-MEG3 is expressed in several human normal tissues, yet is notably absent in various types of human carcinomas 37-39, suggesting it may act as a tumor suppressor." (PMID 34671212, 2021). "Finally, in order to extend the clinical significance of MEG3-mediated pyroptosis in the DDP-induced anti-tumor effect of TNBC, we examined the tumor growth and metastasis ability in vitro and in vivo." (PMID 34326697, 2021). "Maternally expressed 3 (MEG3) lncRNA has been reported as a tumor suppressor." (PMID 34680193, 2021). "MEG3 is a type of lncRNA that has been studied extensively in tumor research." (PMID 34326697, 2021). "A previous study has verified that lncRNA MEG3 could serve as a tumor suppressor to inhibit both proliferation and metastasis of GC." (PMID 34399770, 2021).
tumor (continued). "To determine whether DDP-induced pyroptosis suppresses tumor growth and metastasis via MEG3/NLRP3/caspase-1/GSDMD pathway in vivo, we established a xenograft model of nude mice bearing the MDA-MB-231 cells." (PMID 34326697, 2021). "However, increasing evidence suggests that Meg3 frequently is either lost or depleted in multiple human tumors and tumor cell lines." (PMID 34934045, 2021). "Aside from functioning as a tumor suppressor, emerging evidence suggests that MEG3 may be involved in the regulation of stemness." (PMID 34069546, 2021). "Interestingly, MEG3 expression was significantly downregulated in tumor tissues compared with normal tissues." (PMID 34895065, 2021). "For instance, several groups have observed desirable effects from restoring miR-34 in reducing tumor burden in murine models of NSCLC, with similar efforts having been made to examine the effects of restoring other tumor suppressors such as miR-29, let-7, and MEG3." (PMID 33803619, 2021). "Xenograft tumor models were established to investigate the effect of MEG3 in vivo." (PMID 34895065, 2021). "In the present study, the tumour‐suppressive role of MEG3 was further verified by in vivo assays." (PMID 33332708, 2021). "Moreover, administration of synthetic miRNAs, such as miR-377 mimic, can help increase MEG3 expression and inhibit tumor migration and invasion." (PMID 34322395, 2021). "The maternally expressed MEG3 is the first lncRNA to be found to have tumor suppressor functions." (PMID 33061817, 2020). "Tumor growth was significantly suppressed in pMEG3 mice compared with pcDNA group (p < 0.001); accordingly, tumor weight at the end of the study was lower in MEG3-overexpressing xenografts compared to the control group (p < 0.001)." (PMID 32295169, 2020). "The regulation of PTEN by MEG3 was then confirmed in immunohistochemical analysis of mouse xenografts, showing that the protein was significantly up-regulated in pMEG3-overexpressing tumor compared to controls (p < 0.001)." (PMID 32295169, 2020). "Indeed, in line with recent literature data, we proved that over-expression of MEG3 inhibited cell proliferation, plate colony formation, migration, and invasion ability, as well as spheroid formation and tumor growth in mice." (PMID 32295169, 2020). "Also, transfection and ectopic expression of MEG3 in human cancer cell lines can inhibit tumor cell proliferation." (PMID 33362712, 2020). "Ectopic expression of MEG3 in SW1990 cells inhibited tumor growth in vivo." (PMID 33299646, 2020). "Notably, in multivariate Cox regression analysis, after adjusting for residual tumor after surgery, MEG3 was identified as an independent predictor of PFS (p = 0.002)." (PMID 32295169, 2020). "Moreover, MEG3 affected the Rb pathway, thereby significantly reducing the proliferation of tumor cells." (PMID 31371390, 2020). "In conclusion, our findings suggested that MEG3 was a tumor suppressor in NB and could be a potential target for NB treatment in the future." (PMID 33061817, 2020). "Additionally, mounting studies also verified that lncRNA MEG3 inhibited tumor initiation and progression." (PMID 31938020, 2020). "MEG3 is aberrantly expressed in multiple types of cancers and is assumed as a tumor suppressor." (PMID 32219064, 2020).
tumor (continued). "In fact, several lncRNAs such as HOTAIR (homebox C transcript antisense RNA) or PVT1 (lncRNA plasmacytoma variant translocation 1) behave as oncogenes, whereas others such as MEG3 (maternally expressed 3) or PANDAR (promoter of CDKN1A antisense DNA damage-activated RNA) act as tumor suppressors." (PMID 32214045, 2020). "MEG3 is a maternally imprinted gene functioning as a tumor suppressor." (PMID 31947591, 2020). "In addition, to find out if SUC accumulation is a key point of apoptosis promotion, we measured the fold change in SUC after treating OLP cells with the tumour suppressor lncRNA MEG3." (PMID 31793175, 2020). "In conclusion, numerous studies have shown that MEG3 is a new type of lncRNA tumor suppressor." (PMID 33061817, 2020). "We speculated that the DLK1/MEG3 locus promoted somatotroph differentiation and inhibited tumor proliferation of PitNETs." (PMID 33472171, 2020). "lncRNA MEG3, a tumor suppressor, is closely related to the development of various cancers." (PMID 31938020, 2020). "Then, we found that succinate activated the hypoxia‐inducible factor‐1 alpha (HIF‐1α) pathway and induced apoptosis, which could also be up‐regulated by the tumour suppressor lncRNA MEG3." (PMID 31793175, 2020). "MEG3 is reduced in many cancer cell lines and tumor tissues." (PMID 32655995, 2020). "Previous studies have demonstrated that the expression level of MEG3 is reduced in cancer cells, and upregulation of MEG3 expression could inhibit tumor growth; therefore, MEG3 was initially considered to function mainly as a tumor suppressor." (PMID 33329296, 2020). "Previous studies have shown that MEG3 acts as a tumor suppressor; its expression is lost in a variety of cancer tissues, and overexpression of MEG3 could inhibit tumor formation." (PMID 33329296, 2020). "It was, hence, conjectured that MEG3 methylation might also account for the role of lowly expressed MEG3 in regulating tumor activity, such as metastasis and chemoresistance." (PMID 32618397, 2020). "Taken together, these results suggested that MEG3 inhibited tumor growth and metastasis in vivo." (PMID 33299646, 2020). "In contrast, XIST acts as a ceRNA to increase BCL-2, and it may be upregulated to reverse the tumor suppressor function of MEG3." (PMID 32629922, 2020). "In addition, overexpression of MEG3 significantly represses the growth and migration ability of OS cells, confirming the tumor suppressive role of MEG3 in OS progression." (PMID 32249459, 2020). "Many researches showed that MEG3 was a tumor suppressor in colorectal cancer and other cancers." (PMID 32065781, 2020). "In vitro experiments showed that restoring the expression of MEG3 could inhibit cancer cells proliferation and induce their apoptosis, and a similar tumor inhibition effect was found in nude mice." (PMID 32669097, 2020). "The results demonstrated that lncRNA MEG3 could suppress the tumor growth, tumor metastasis and formation; and meanwhile E-cadherin had the same effects on tumor growth, tumor metastasis and formation." (PMID 31938020, 2020). "Deletion is the most frequent mechanism for MEG3 silencing in tumor cells." (PMID 33142861, 2020). "MEG3 can inhibit the occurrence of tumor through various aspects." (PMID 32669097, 2020). "Concerning lncRNA matriarchal‐expressed gene 3 (MEG3) studied here, its expression was down‐regulated and even lost in tumor tissues of brain, bladder, bone marrow, breast, cervix, colon, liver, lung, and prostate, as compared with normal tissues of these organs." (PMID 32618397, 2020). "Therefore, it is suggested that MEG3 functions as a tumor-suppressor via regulating miR-21-5p, inhibiting the tumor growth in CC." (PMID 33371204, 2020).
tumor (continued). "MEG3 was recognized as a tumor suppressor deponed on recent researches." (PMID 32669097, 2020). "MEG3, a myeloid-related lncRNA, plays a tumour suppressor role in various solid neoplasms." (PMID 31842887, 2019). "MEG3 is another lncRNA with fold change 0.09 in the present study, which has been widely studied in carcinomas and may be involved in tumorigenesis as tumor suppressor." (PMID 31196171, 2019). "Moreover, MEG3 levels were decreased in tumor tissues belonging to stages III and IV as compared to those of stage I." (PMID 31729423, 2019). "In addition, Meg3 seems to act as a tumor suppressor and as an important regulator of cellular proliferation." (PMID 30765776, 2019). "We aim to explore the influence of epigenetic regulation of MEG3 on tumor cell migration, invasion, proliferation and apoptosis and to study the previous targeting relationship among these three functions and the influence of MEG3 reintroduction on tumor growth." (PMID 31584879, 2019). "Other lncRNAs, including GAS5, ZFAS1, XIST, and MEG3, function as tumor suppressors." (PMID 30764831, 2019). "Taken together, MEG3 was found that it could inhibit the Wnt/β-catenin axis to act as a tumor suppressor." (PMID 31133028, 2019). "MEG3 is defined as a tumor suppressor, but also regulates the balance of Treg cells and Th17 cells; downregulation of MEG3 increases forkhead box P3 (FOXP3) expression and inhibits retinoic acid receptor-related orphan receptor γt (RORγt) expression, to tip the balance in favor of Treg cells." (PMID 31547203, 2019). "miR-484 is a tumor suppressor miRNA between MEG3 and Decorin in our module." (PMID 31182759, 2019). "Enforced expression of MEG3 limits tumor cell proliferation." (PMID 31141943, 2019). "H19, KCNQ1OT1, and MEG3 are also known imprinted genes that function as tumor suppressors." (PMID 30732658, 2019). "Collectively, these data indicate that DLK1 is a potential prognostic factor for AML patient OS and the tumor-suppressing abilities of MEG3 may be overwhelmed by DLK1 expression and/or CpG site-specific signatures of its downstream miRNAs." (PMID 30876483, 2019). "Therefore, we demonstrated a negative correlation between MEG3 and miR-181a-5p and found that upregulation of MEG3 in vivo can inhibit tumor growth." (PMID 31584879, 2019). "In addition, a tumor xenotransplantation model was established to study the influence of MEG3 on tumor growth in vivo." (PMID 31584879, 2019). "LncRNAs can be divided into three types: well-studied tumor-suppressor genes (including LncRNA antisense noncoding RNA in the INK4 locus (ANRIL) and lncRNA maternally expressed gene 3 (MEG3)), oncogenes, tumor-suppressor genes, and duplex lncRNAs according to their functions." (PMID 29229673, 2018). "Importantly, overexpression of MEG3 suppressed the growth of xenograft tumor and improved chemotherapy sensitivity of A375 cells to cisplatin and 5-FU treatment." (PMID 29808164, 2018).
tumor (continued). "Moreover, the MEG3 lncRNA has been described as a tumor suppressor; MEG3 levels were significantly downregulated in patients with NSCLC." (PMID 29435111, 2018). "Overexpressed MEG3 can arrest cell cycle, inhibit tumor cell proliferation, and promote apoptosis." (PMID 29416703, 2018). "Similarly, when we checked the clinical association of the lncRNAs screened in the present study in TANRIC database, lncRNAs H19, MEG3 and MALAT1 showed significant association with tumor stage and HOTAIR had a significant association with patient survival." (PMID 29719612, 2018). "LncRNA MEG3, a tumor suppressor, has been reported to play important roles in some cancers, but the role of MEG3 in GBC remains largely unknown." (PMID 30282996, 2018). "Similarly MEG3, a lncRNA with tumour suppressor properties, was downregulated in our microarray results." (PMID 30038703, 2018). "It has been demonstrated that restoring of MEG3 expression may contribute to the suppression of tumor cell proliferation and the induction of cell apoptosis." (PMID 30282972, 2018). "Taken together, these data indicated that upregulation of MEG3 inhibited tumor growth in vivo." (PMID 30282996, 2018). "Our study for the first time demonstrated that MEG3 acts as a tumor suppressor by negatively regulating the activity of PKM2 and β-catenin in hepatocarcinogenesis and might serve as a prognostic biomarker and molecular therapeutic target." (PMID 29449541, 2018). "A number of previous studies have identified MEG3 as a classical tumor suppressor." (PMID 30386180, 2018). "Multiple functions for MEG3 in cancer have been described, Locally, expression is inversely correlated with the nearby tumor suppressor DLK1, which it may regulate." (PMID 29113413, 2017). "MEG3 expression is substantially reduced in OSCC tumor cell lines." (PMID 27802187, 2017). "In the CRC, MEG3 might act as a tumor suppressor gene and contribute to tumorigenesis through inhibiting cancer cell proliferation." (PMID 28658310, 2017). "MEG3, a tumour suppressor, has a great capacity for prognosis in many cancers." (PMID 28814798, 2017). "MEG3 expression was reduced in several cancers, and up-regulation of MEG3 inhibits tumor growth." (PMID 28486418, 2017). "We found that hypermethylation of MEG3 DMR sites within a CTCF binding domain is associated with increased miRNA expression (potentially by inhibiting CTCF binding and its enhancer-blocking effect ) and higher tumor aggressiveness." (PMID 28506242, 2017). "Therefore, this meta-analysis evaluated the value of the MEG3 with tumor metastasis, progression, and survival." (PMID 28157702, 2017). "Furthermore, MEG3 down-regulation correlates positively with increased tumor size, advanced FIGO stage, metastasis of lymph nodes and HR-HPV positivity." (PMID 28637507, 2017). "In these included studies, the level of MEG3 expression was determined in collected tumor tissues." (PMID 28157702, 2017). "At last, we revealed that MEG3 functioned as a tumor suppressor by regulating miR-21-5p." (PMID 28740189, 2017). "However, MEG3 expression missing was found in a variety of tumor cell lines, including brain, bladder, bone marrow, breast, cervix, colon, liver, lung and prostate." (PMID 29029424, 2017). "Furthermore, the discovery that WT1 cooperates with TET2 to upregulate MEG3 expression places TET2-WT1-MEG3 signaling axis as a central tumor suppressive pathway in AML, therefore emphasizing the potentials of this axis in AML diagnosis and therapy." (PMID 28400619, 2017).